GZMB (granzyme B)
Diseases named in the same sentence as GZMB in open-access papers (continued):
Sharing a sentence is not in itself a finding about the gene and the disease.
B cell lymphoma (3 papers, 2016 to 2025). "To examine the role of GzmB in GVT effect mediated by CD4+CD25− Tcon cells, we utilized A20 tumor cells, which are B cell lymphoma cells derived from BALB/c strain and express normal level of MHC class II." (PMID 27774524, 2016). "Although the recall responses to MHV-68 induced more effector molecule production (GzmB+IFN-γ+) in the engineered cells, the EμMyc B cell lymphoma challenge showed worse tumor protection with larger tumors and shorter survival time in recipients of the engineered cells." (PMID 40857407, 2025). "In another study, it has been shown that short-term ALT-803 stimulation significantly increased granzyme B and perforin expression, as well as IFN-γ production in human NK cells, resulting in increased ADCC directed by an anti-CD20 mAb against B cell lymphoma cells." (PMID 30601063, 2019).
cardiac hypertrophy (3 papers, 2021 to 2023). "This is further corroborated by the study showing that a deficiency of granzyme B leads to reduced cardiac fibrosis and hypertrophy." (PMID 37374379, 2023). "In a cardiac model of fibrosis, genetic GzmB deficiency led to reduced angiotensin II-induced cardiac hypertrophy and less fibrotic activity." (PMID 33674592, 2021).
Cerebral ischemia (3 papers, 2015 to 2024). Restriction of arterial blood supply to the brain associated with insufficient oxygenation to support the metabolic requirements of the tissue. "SERPINA3 can attenuate neuronal injury by interfering with granzyme B-mediated neuronal death after cerebral ischemia." (PMID 36959823, 2023).
cholangiocarcinoma (3 papers, 2021 to 2024). A carcinoma that arises from the intrahepatic biliary tree (intrahepatic cholangiocarcinoma) or from the junction, or adjacent to the junction, of the right and left hepatic ducts (hilar cholangiocarcinoma). "In this study, we newly demonstrated that the density of CD8+Granzyme B+ T cells, which are considered to be high-quality effector T cells, to be a stronger prognostic indicator in cholangiocarcinoma." (PMID 35346322, 2022). "This study suggests that the densities of Granzyme-B+CD8+ effector T cells and non-exhausted PD-1−EOMES−CD8+ T cells and the PD-L1 status in the tumor-associated macrophages are prognostic makers in cholangiocarcinomas." (PMID 35346322, 2022).
Cirrhosis (3 papers, 2018 to 2025). A chronic disorder of the liver in which liver tissue becomes scarred and is partially replaced by regenerative nodules and fibrotic tissue resulting in loss of liver function. "MAIT cells from patients with cirrhosis produced more IL-17 and granzyme B than those from control individuals, whereas the frequency of IFN-γ+ or TNF+ MAIT cells was high, but not different between the two groups." (PMID 29858567, 2018). "Seven DEGs (TYMP, TYROBP, CD14, TGFBI, LILRA2, GNLY, and GZMB) were common to HCC, cirrhosis, and CHB when compared to healthy controls." (PMID 35265561, 2022).
clear cell renal cell carcinoma (3 papers, 2024 to 2025). "Another study by them demonstrated that the administration of anti-VISTA treatment led to a significant increase in the percentage of granzyme B+ Perforin+ CD8+ T cells in most patients with clear cell renal cell carcinoma." (PMID 38357542, 2024).
Conjunctiva (3 papers, 2018 to 2024). "During acute infection, the eyes showed retinal layer disorganization, retinitis, vitritis, and focal choroiditis, with mild cellular infiltration and increased expression of tumor necrosis factor, interferon-γ, granzyme B, and perforin." (PMID 29802245, 2018).
esophageal squamous cell carcinoma (3 papers, 2020 to 2024). Esophageal squamous cell carcinoma (ESCC) is a type of esophageal carcinoma (EC) that can affect any part of the esophagus, but is usually located in the upper or middle third. "In esophageal SCC, CXCL10 and CCL5 have been positively correlated with CD8 and Granzyme B at the mRNA level, and tissue expression of CCL5 was positively associated with post-surgical patient survival." (PMID 33925140, 2021). "In esophageal squamous cell carcinoma (ESCC), IL-17 promotes humoral immunity mediated by B cells by inducing chemokines and enhances the tumor-killing ability of B cells indirectly and directly by stimulating the production of IgG and granzyme B." (PMID 39906741, 2024).
fibrosis (3 papers, 2020 to 2022). the formation of excess fibrous connective tissue in an organ or tissue in a reparative or reactive process. "Together, this suggests that GzmB appears to have an important contribution to the development of fibrosis in skin following exposure to I/R." (PMID 33674592, 2021).
hantavirus infection (3 papers, 2013 to 2021). "This may suggest a possible role of extracellular granzyme B in causing increased vascular permeability, a common hallmark of hantavirus infection." (PMID 33763658, 2021). "Intracellular GzmB has been shown to be expressed in activated CTLs or NK cells in lungs in severe infant respiratory syncytial virus infection and lungs of fatal PUUV cases, as well as in blood in human hantavirus infection and in a macaque model." (PMID 26873376, 2016).
HCMV infection (3 papers, 2014 to 2020). "Likewise, NK cells from mice treated with rapamycin to block the mTOR pathway displayed defects in proliferation, and IFN-γ and granzyme B productions resulting in elevated viral burdens upon murine cytomegalovirus infection." (PMID 24795729, 2014). "Granzyme B and Perforin measurements, in addition to IFN-γ detection, while interrogating HCMV-specific CD8+ T cells should facilitate the detection of an active ongoing immune response to the virus, including the detection of a reactivation of HCMV infection." (PMID 29783767, 2018).
Hypercholesterolemia (3 papers, 2013 to 2025). An increased concentration of cholesterol in the blood. "Consistent with our in vitro findings, hypercholesterolemia patients undergoing statin therapy displayed a reduced proportion of granzyme B‐ and perforin‐producing Vδ2 T cells but among αβ T cells, only perforin‐producing CD8 T cell numbers were decreased." (PMID 40264329, 2025). "We set plasma granzyme B levels as a dependent variable and age, gender, BMI, HTN, hypercholesterolemia, current smoker, and patient history of previous ACS as independent variables." (PMID 24307760, 2013).
infectious mononucleosis (3 papers, 2015 to 2025). A condition characterized by an increase in mononuclear white blood cells and swollen lymph nodes, which is usually caused by infection with the Epstein-Barr virus. "In summary, EBV-induced infectious mononucleosis is characterized by dysregulated expression of multiple immune markers in peripheral blood.The high expression of GzmB and low expression of CD28 are associated with LI in IM, and further mechanistic exploration is warranted." (PMID 41321447, 2025). "Here, we show that patients with recently diagnosed infectious mononucleosis caused by Epstein-Barr virus (EBV) have high circulating levels of GzmB that may be derived from infected B cells early in course of disease." (PMID 26191409, 2015).
LGL leukemia (3 papers, 2008 to 2022). "It will be important to determine if direct CTL killing of neutrophils is a uniting feature of both disorders, as it could be responsible for the neutropenia observed in LGL leukemia and be a potent inducer of citrullinated and granzyme B-cleaved autoantigens in both diseases." (PMID 35646651, 2022). "Bone marrow trephines from T-LGL leukemia patients showed interstitial clusters and intrasinusoidal linear infiltrations of CD3+/CD8+/CD57+/granzyme B+ lymphocytes, reactive lymphoid nodules, and decreased or normal granulocyte precursor count with left-shifted maturation." (PMID 18474096, 2008).
liver disease (3 papers, 2013 to 2025). "Of note, levels of Granzyme B expression remained equal across all stages of liver disease and healthy controls." (PMID 41028194, 2025).
lymph node metastases (3 papers, 2014 to 2024). "A high density of Granzyme B (GrB) was found to be associated with fewer lymph node metastases (LNM) and better survival in oral cavity carcinomas." (PMID 32635549, 2020). "When comparing clinicopathological characteristics, the low GzmB/CCR8 ratio group from the ROI protocol had significantly higher rates of lymph node metastasis (34.1% vs. 12.5%, respectively, P = 0.035) and pleural invasion (22.0% vs. 5.0%, respectively, P = 0.048)." (PMID 38783281, 2024).
mastitis (3 papers, 2018 to 2025). Inflammation of breast tissue during lactation or postpartum due to an obstructed duct or infection. "In the mastitis sample, clear co-expression of granzyme B in CD45 cells (27.0%) as well as perforin in CD45 cells (34.1%) is evident." (PMID 30181507, 2018). "Specifically, in subclinical mastitis milk, the expression levels of five cytokines—IFN-γ, IL-2, TNF-α, IL-17, and GZMB—were significantly higher in WC1+ γδ T cells compared to healthy cows." (PMID 41142813, 2025). "In the milk of subclinical mastitis in this study, WC1+ γδ T cells exhibited significant upregulation of IFN-γ, IL-2, TNF-α, IL-17, and GZMB." (PMID 41142813, 2025). "However, we did observe a significantly lower percentage of granzyme B+ memory CD8+ T cells in breastmilk of mothers with multiple children, which might be related to the higher chance of developing mastitis in primiparous women." (PMID 39435660, 2024).
measles (3 papers, 2017 to 2021). A highly contagious viral infection caused by the measles virus. "P4 treatment was associated with a significantly reduced granzyme B response at 34 weeks of gestation to measles, influenza A and TTOX." (PMID 29973928, 2018). "Although granzyme B production at baseline was below 20 per 106 SFCs, when measurable, PBMC from RU486 treated patients produced a greater number of granzyme B SFCs in response to measles and influenza A whole lysate, and FEC peptide pool measured 72 h post RU486." (PMID 29973928, 2018). "However, granzyme B responses against TTOX were downregulated in the second trimester, and a similar trend was observed in responses against measles (p = 0.0525) (data not shown)." (PMID 28966619, 2017).
myocarditis (3 papers, 2017 to 2024). Myocarditis is a condition that is characterized by inflammation of the heart muscle (myocardium). "These imaging approach of Granzyme B activity can permit non-invasive imaging of immune-mediated myocarditis in vivo and reveal therapeutic effect of pharmacologic interventions." (PMID 28955332, 2017).
oral squamous cell carcinoma (3 papers, 2024 to 2025). "In one study researching oral squamous cell carcinoma, increased numbers of GZMB-expressing Tregs were found in comparison with control patients." (PMID 40002821, 2025). "GZMB has been localized in many cancer cells, i.e. breast, lung and urothelial carcinomas, nasal-type NK/T-cell lymphoma, oral squamous cell carcinoma." (PMID 40766321, 2025).
preeclampsia (3 papers, 2021 to 2024). Preeclampsia is a hypertensive disorder of pregnancy that is characterized by new-onset hypertension with proteinuria presenting after 20 weeks of gestation, and depending on mild or severe forms may initially present with severe headache, visual disturbances, and hyperreflexia. "Elevated GZMB in preeclampsia inhibits invasion and migration of trophoblasts." (PMID 37501789, 2023). "Furthermore, significantly reduced granzyme B content was observed in the case of CD8+ T cells in women diagnosed with EO preeclampsia compared to healthy women." (PMID 34829838, 2021).
prostate tumors (3 papers, 2017 to 2023). "PCa tissues obtained from RP displayed almost no expression of Granzyme-B (GZMB) and Perforin 1 (PRF1), markers of cytolytic activity, indicating that T cells infiltrating prostate tumors are functionally impaired." (PMID 37090711, 2023).
relapsing-remitting MS (3 papers, 2022 to 2023). "Also, increased circulating T lymphocytes with the ability to express GzmB were found in the peripheral blood from relapsing-remitting MS (RRMS) patients treated with fingolimod (FTY), and particularly during relapses, when compared to RRMS patients without FTY." (PMID 35197967, 2022). "Further phenotypical and functional analysis showed that circulating γδ T cells in relapsing-remitting multiple sclerosis (RRMS) patients have a reduction in the circulating CCR5+ γδ T-cell subset with decreased EOMES and granzyme B mRNA abundance and increased production of IFN-γ." (PMID 37854609, 2023).
renal cell carcinoma (3 papers, 2022 to 2025). "A study of renal cell carcinoma showed significant reductions in CD8+ T cell infiltration and granzyme B and perforin levels in tumor tissues with high expression of GLUT-1 and LDHA." (PMID 39408814, 2024).
respiratory infections (3 papers, 2021 to 2023). "In addition to perforin and granzyme B, a process also occurs in other respiratory infections." (PMID 34603300, 2021).
sarcoidosis (3 papers, 2022 to 2025). Sarcoidosis is a multisystemic disorder of unknown cause characterized by the formation of immune granulomas in involved organs. "By contrast, T cells from sarcoidosis patients exhibited clonal expansion of terminally differentiated CD8+ effectors that expressed high levels of effector genes, including CCL5, GZMB, PRF1, IFNG, KLRG1 and ZEB2." (PMID 40469525, 2025). "In sarcoidosis patients, CD8+ T cells were predominantly GZMB+, whereas in active TU and healthy controls, the majority of CD8+ T cells consisted of naive and memory T cells." (PMID 40469525, 2025). "Furthermore, non-synonymous SNPs in LILRB2, GZMB, APOL1, CNN2, SWAP70, and CSF1R were shown in over 50% of sarcoidosis patients." (PMID 35860586, 2022).
scleroderma (3 papers, 2023 to 2024). Scleroderma is a rare autoimmune connective tissue disorder characterized by abnormal hardening of the skin and, sometimes, other organs. "GzmB has also been investigated in other scleroderma-associated vasculopathies." (PMID 36830757, 2023). "It has been reported that the cytotoxic killing mediated by perforin and granzyme B can generate autoantigens that foster and/or prolong the immune response, as self-protein fragments generated by granzyme B are autoantibody targets in scleroderma disease." (PMID 38592689, 2024). "This led the authors to speculate that GzmB may account for some of the vascular defects observed in scleroderma via the generation of antiangiogenic factors like angiostatin." (PMID 36830757, 2023).
skin tumor (3 papers, 2022 to 2025). "Further, skin tumor progression activated T cells and NK cells indicated by elevated expression of IFN-γ and Granzyme B in skin tumors." (PMID 40282557, 2025). "As dietary GLSF prevents UV-induced skin tumor formation and expression of T-cell activation markers CD8 and Granzyme B, we next examined whether treating mice with GLSF has any protective effects against UV-induced immunosuppression." (PMID 35312729, 2022).
Splenomegaly (3 papers, 2021 to 2024). Abnormal increased size of the spleen. "There was increased splenomegaly with RD2 by infiltration of cytotoxic CD8+ T cells expressing Perforin and Granzyme B. These alloimmune T cells showed a pro-inflammatory IL-2 and IFN-γ expression profile as well." (PMID 34177940, 2021).
visceral leishmaniasis (3 papers, 2010 to 2019). A severe form of leishmaniasis characterized by irregular bouts of fever, substantial weight loss, swelling of the spleen and liver, and anemia (which may be serious). "A support for this notion came from ELISA and FACS analysis where the epitopes as a cocktail induced CD8+ IFN-γ and Granzyme B levels significantly in treated visceral leishmaniasis subject which suggests the immunogenic ability of the selected epitopes." (PMID 30242172, 2018).
acute GVHD (2 papers, 2024). "A significant decrease in the Treg:Th cell ratio at 2 weeks after allo-HSCT transplantation is associated with the development of acute GVHD, and a high probability of developing acute GVHD was also observed in patients with a low number of granzyme B+ Treg." (PMID 39768148, 2024). "On the other hand, GzmB-mediated activation-induced death of CD4+ T cells inhibits murine acute GVHD, while GzmB contributes to the optimal graft-versus-tumor effect mediated by CD4+ T cells." (PMID 38846935, 2024). "Notably, host-derived serine protease inhibitor 6 also provides GzmB-independent protection of intestinal epithelial cells in acute GVHD, suggesting that it may interact with other proteases." (PMID 38846935, 2024).
Alzheimer disease (2 papers, 2020 to 2023). A progressive, neurodegenerative disease characterized by loss of function and death of nerve cells in several areas of the brain leading to loss of cognitive function such as memory and language. "We have recently demonstrated that Eomes+ Th cells infiltrated into the CNS of mouse models of amyotrophic lateral sclerosis (ALS) and Alzheimer’s disease (AD) secrete neurotoxic granzyme B after encounter with ectopically expressed ORF1 antigen encoded by L1 retrotransposon." (PMID 36980209, 2023). "Fifteen of the altered proteins mapped to 12 different pathways: pathological pathways included Apoptosis signaling pathway (P00006, FASL, Granzyme B), FAS signaling pathway (P00020, FASL) and Alzheimer disease-presenilin pathway (P00004, E-Cadherin)." (PMID 32804078, 2020). "Fourteen different proteins mapped to 11 different pathways, pathological pathways include: Apoptosis signaling pathway (P00006, TNF-R2, FASL, Granzyme B) and FAS signaling pathway (P00020, FASL) and Alzheimer disease-presenilin pathway (P00004, E-Cadherin)." (PMID 32804078, 2020).
amyotrophic lateral sclerosis (2 papers, 2013 to 2023). Amyotrophic lateral sclerosis (ALS) is a neurodegenerative disease characterized by progressive muscular paralysis reflecting degeneration of motor neurons in the primary motor cortex, corticospinal tracts, brainstem and spinal cord. "The top canonical pathway in hP29SN stromal cells affected by 1α,25(OH)2D3, 25(OH)D3, and 24R,25(OH)2D3 is “Amyotrophic Lateral Sclerosis Signaling” (p = 0.006), “Granzyme B Signaling” (p = 0.002), and “DNA Double-Strand Break Repair by Homologous Recombination” (p = 0.003), respectively." (PMID 24116037, 2013).
anti‐synthetase syndrome (2 papers, 2021 to 2023). "Epidemiologically, anti‐synthetase syndrome is strongly associated with prior respiratory insults, and an immunogenic, granzyme B‐cleavable of histidyl tRNA synthetase has been identified in alveolar epithelium." (PMID 33552511, 2021). "All populations were detected in all seven patients although memory PB T cells mainly consisted of GZMB+ EM T cells in patient 4 with antisynthetase syndrome (ASyS)." (PMID 37522383, 2023).
bladder tumor (2 papers, 2023 to 2025). "We noted that both IFNγ and GzmB production were drastically reduced in CD8+ T cells from tumor site as compared to their PBMC counterpart, strongly suggesting the functional impairment of T cells at the bladder tumor site." (PMID 37566017, 2023).
brain tumor (2 papers, 2024 to 2025). "Using tissue microarrays of 158 brain tumour samples, we assessed CD3, CD4, CD8, CD20, CD138, Granzyme B (GzmB), 5-Lipoxygenase (5-LOX), Programmed Death-Ligand 1 (PD-L1), O-6-Methylguanine-DNA Methyltransferase (MGMT) and Transglutaminase 2 (TG2) expression by immunohistochemistry (IHC)." (PMID 38816839, 2024).
bullous dermatoses (2 papers, 2018 to 2022). "Granzyme-B is upregulated in injured skin and chronic skin diseases, such as pemphigoid and atopic dermatitis." (PMID 35327667, 2022). "Because of its ability to cleave anchoring proteins of the dermal-epidermal junction (DEJ), in addition to E-cadherin and filaggrin, studies propose that granzyme-B exacerbates dermal-epidermal separation in pemphigoid and epidermal barrier disruption in dermatitis." (PMID 35327667, 2022).